RBM39 (RNA binding motif protein 39)
Description:
RNA-binding protein that acts as a pre-mRNA splicing factor. Acts by promoting exon inclusion via regulation of exon cassette splicing. Also acts as a transcriptional coactivator for steroid nuclear receptors ESR1/ER-alpha and ESR2/ER-beta, and JUN/AP-1, independently of the pre-mRNA splicing factor activity (By similarity).
Synonyms: CAPERalpha; HCC1; RNPC2; CC1.3; CAPER; fSAP59
Tractability: Small molecule: a structure with a bound ligand is known. PROTAC: UniProt records ubiquitination sites on it; ubiquitination databases record sites on it; its protein half-life has been measured.
Gene: Protein-coding gene on chromosome 20 (35,701,347 to 35,742,312, reverse strand). Ensembl gene ENSG00000131051.
Subcellular location: Nucleus speckle
Subcellular location (Human Protein Atlas): Nuclear speckles; Nucleoplasm; Centriolar satellite; Microtubules
Pathways (Reactome):
Metabolism of RNA: mRNA Polyadenylation; mRNA Splicing - Major Pathway
Gene Ontology:
Molecular function: protein binding; RNA binding; U1 snRNP binding; nucleic acid binding; RS domain binding
Biological process: regulation of mRNA splicing, via spliceosome; RNA processing; mRNA processing; regulation of gene expression; regulation of RNA metabolic process
Cellular component: nuclear speck; protein-containing complex; nucleoplasm; nucleus
Genetic constraint (gnomAD): Loss-of-function variants: 9 observed, 59.68 expected, observed/expected ratio (o/e) 0.15, 90% interval 0.09 to 0.26. The upper end of that interval is the gene's LOEUF score, 0.26, which puts it in group 1 of 6, group 1 being the genes least tolerant of losing a copy. Missense variants: 198 observed, 560.03 expected, observed/expected ratio (o/e) 0.35, 90% interval 0.31 to 0.4. Synonymous variants: 162 observed, 180.22 expected, observed/expected ratio (o/e) 0.9, 90% interval 0.79 to 1.02.
Homologues: Orthologues: chimpanzee RBM39 (100% identical), dog RBM39 (100% identical), macaque RBM39 (100% identical), pig RBM39 (100% identical), rabbit RBM39 (100% identical), mouse Rbm39 (99% identical), chimpanzee RBM39 (95% identical), guinea pig RBM39 (92% identical), rat Rbm39 (91% identical), tropical clawed frog rbm39 (87% identical), zebrafish rbm39a (81% identical), zebrafish rbm39b (77% identical). Paralogues in human: RBM23 (52% identical), RBM19 (18% identical), NUCLEOLIN (17% identical), HNRNPD (17% identical), HNRNPAB (16% identical), HNRNPDL (16% identical), MSI2 (15% identical), MSI1 (14% identical), RBMX (14% identical), HNRNPA1 (14% identical), RBMXL1 (14% identical), TIAL1 (14% identical), and 24 more.
Diseases named in the same sentence as RBM39 in open-access papers:
RBM39 is named in the same sentence as 66 diseases in open-access papers, as found by Europe PMC text mining. Sharing a sentence is not in itself a finding about the gene and the disease. The quoted sentences say what the papers report.
liver cancer (12 papers, 2021 to 2026). An epithelial or non-epithelial malignant neoplasm that arises from the liver. "RBM39 is up-regulated as a splicing factor in a variety of cancers, including NSCLC, liver cancer, and gastric cancer, and its loss is lethal to cancer cells." (PMID 40465651, 2025). "For instance, in liver cancer, elevated arginine levels regulate the transcription of metabolism-related genes by binding to RBM39, thereby modulating metabolic reprogramming and promoting tumor progression." (PMID 41218081, 2025). "Recent research has shown that RBM39 mediates the increase in asparagine synthesis in liver cancer, leading to enhanced arginine uptake and the formation of a positive feedback loop to maintain high levels of arginine, thus promoting carcinogenic metabolism." (PMID 39044280, 2024). "Researchers have found that arginine content is increased in mouse models and human liver cancer cells, and arginine interacts with RNA-binding protein 39 (RBM39) to control the expression of metabolic genes." (PMID 39612465, 2024). "In terms of mechanism, arginine alters the metabolism of liver cancer by attaching to RNA-binding protein 39 (RBM39) to regulate the expression of metabolic genes." (PMID 38601162, 2024). "Importantly, using mouse models of liver cancer, we show that RBM39 and SF3B1 inhibitors are effective in targeting both preneoplastic lesions and aggressive tumours expressing oncogenic RAS." (PMID 41986348, 2026). "RBM39 depletion by the molecular glue degrader indisulam blocks pro-oncogenic metabolic reprogramming in hepatocellular carcinoma, suggesting that RBM39 is a therapeutic target in liver cancer." (PMID 37804830, 2023). "A study on the microenvironment of liver cancer found that high levels of arginine in liver cancer cells were able to control gene expression and perform metabolic reprogramming after binding to RNA-binding motif protein 39 (RBM39), giving tumor cells the ability to divide indefinitely." (PMID 39852139, 2025). "RNA binding motif protein 39 (RBM39), also referred to as HCC1 (hepatocellular carcinoma 1) and CAPER, was first identified as a novel nuclear antibody purified from liver cancer patients." (PMID 40302803, 2025). "Immunoblotting confirmed loss of ARG1 and AGMAT and increased levels of RBM39 and ASNS in tumors of liver cancer patients compared to adjacent non-tumor tissue." (PMID 37804830, 2023).
hepatocellular carcinoma (11 papers, 2021 to 2025). A malignant tumor that arises from hepatocytes. "Silencing RBM39 has been shown to suppress PI3K/AKT activity in hepatocellular carcinoma (HCC) and acute myeloid leukemia (AML), leading to impaired cell proliferation and tumor growth." (PMID 41300971, 2025). "Apart from arginine’s effects on mitochondria and lysosomes, a recent study showed that arginine binds to the splicing factor RNA-binding protein 39 (RBM39) in hepatocellular carcinoma (HCC) cells." (PMID 39920310, 2025). "Tumors actively take up arginine via cationic amino acid transporters, as documented in the context of hepatocellular carcinoma, which bind to the RNA-binding motif protein 39 (RBM39) for further metabolic reprogramming." (PMID 39107856, 2024). "RBM39 was discovered as an autoantigen in a cirrhotic patient who later acquired hepatocellular cancer." (PMID 35989423, 2022). "In patients with hepatocellular carcinoma, RBM39 was first identified as an autoantigen whose overexpression reduced tumour angiogenesis and growth and inhibited v‐Rel‐mediated lymphocyte transformation." (PMID 35989423, 2022). "RBM39 was initially identified as the autoantigen from a patient with liver cirrhosis who later developed hepatocellular carcinoma." (PMID 34389703, 2021). "According to previous studies, RBM39 is considered to be a novel antigen identified from patients with hepatocellular carcinoma, showing high levels of expression in hepatocellular carcinoma." (PMID 34389703, 2021). "This intriguing study revealed first time that targeting the cancer‐specific arginine binding protein RBM39 with indisulam to promote its degradation could treat hepatocellular carcinoma (HCC) with high tumoral arginine levels across various models." (PMID 40411419, 2025). "However, whether and how RBM39 regulates BER in hepatocellular carcinoma (HCC) remain unclear." (PMID 40364450, 2025).
acute myeloid leukemia (10 papers, 2021 to 2026). Acute myeloid leukemia (AML) is a group of neoplasms arising from precursor cells committed to the myeloid cell-line differentiation. "RBM39-mediated alternative splicing is also involved in the carcinogenesis and progression of multiple cancers, including acute myeloid leukemia (AML), breast cancer, colorectal cancer and lung cancer." (PMID 39048555, 2024). "Other examples include RBM39 in Acute Myeloid Leukemia or RBM11 in glioblastoma cells, among others." (PMID 34439272, 2021). "Interestingly, RBM39 degradation was described as a biomarker of indisulam response in acute myeloid leukemia and DCAF15 levels were shown to correlate with indisulam response in hematopoietic and lymphoid cancers." (PMID 35534224, 2022). "For instance, DCAF15 is upregulated in some acute myeloid leukemia (AML) patients with respect to normal hematopoietic progenitors and AML cells which showed strong dependency on RBM39 expression." (PMID 35406598, 2022). "In acute myeloid leukemia (AML), it has been reported that the degradation of RBM39 represses cassette exon inclusion and promotes intron retention within mRNAs encoding HOXA9 targets and in other RNA-binding proteins (RBPs) preferentially required for AML survival." (PMID 38789724, 2024). "In the same line, the anti-cancer sulfonamide compound E7820, which degrades the splicing factor RBM39 is being assessed in MDS, acute myeloid leukemia (AML), or chronic myelomonocytic leukemia (CMML) (NCT05024994), which have shown acceptable safety." (PMID 37880792, 2023).
breast cancer (10 papers, 2010 to 2025). A primary or metastatic malignant neoplasm involving the breast. "RBM39 splices VEGF isoforms in metastatic breast cancer cells and loss of RBM39 in sarcoma cells alters VEGF isoform ratio towards more mitogenic/angiogenic forms of VEGF19." (PMID 27324164, 2016). "A similar mammary tumor phenotype developed in caveolin-1 knockout mice that was also associated with the induction of several stem/progenitor cell markers, including RBM39, as found in the present study." (PMID 22538444, 2012). "Therefore, the importance of RBM39 in breast cancer biology has been mostly linked to its role in transcriptional regulation." (PMID 36477312, 2022). "PCa vs control comparisons revealed some startling increases of mRNA levels of: ETV1, a gene that directs androgen metabolism and confers aggressive PCa; FASN, a fatty acid metabolism gene highly up-regulated in PCa; RBM39, a gene implicated in colorectal and breast cancer progression." (PMID 28143451, 2017). "In addition, RBM39 was also overexpressed in mouse models of breast cancer and was associated with increased estrogenic sensitivity, indicating that it could play an important role in the early development of ER-positive breast cancer." (PMID 34389703, 2021). "Our results also support the idea that the splicing regulatory activity of RBM39 is important for breast cancer cell biology and adaptive response towards cisplatin." (PMID 36477312, 2022). "RBM39 is upregulated in most cancers and its inhibition is lethal or cytostatic in several cellular models of breast cancers." (PMID 36477312, 2022). "Through the analysis and identification of human breast cancer samples, it was found that the overexpression of RBM39 experienced cytoplasmic-to-nuclear metastasis in the process of breast cancer metastasis from pre malignant to ductal carcinoma." (PMID 34389703, 2021). "Studies have found that RBM39 is highly expressed in breast cancer tissues and can promote tumor cell proliferation." (PMID 34804951, 2021). "A bioinformatics analysis also showed that RBM39, a target gene of miR-494, can be used as a biomarker to predict trastuzumab resistance in breast cancer." (PMID 34804951, 2021). "A large number of data suggested that RBM39 regulated the transcriptional activity of ERs and PRs and was involved in the progression of human breast cancer." (PMID 34389703, 2021). "RBM39 was expressed at high levels in human breast cancer tissues, but it was almost undetectable in normal breast tissues." (PMID 34389703, 2021). "Although these observations have fuelled the idea that inhibiting RBM39 might be a promising therapeutic opportunity for breast cancers, the exact function of RBM39 in cancer in general and in breast cancer in particular remains unclear." (PMID 36477312, 2022). "RBM39 is a coactivator of ER, ER, and Activator Protein‐1 (AP‐1) component c‐Jun, which binds transcription and mRNA precursor processing together and effectively boosts their transcriptional activity, hence encouraging breast cancer growth." (PMID 35989423, 2022). "Notably, RBM39 is upregulated in most cancers, and the inhibition of its function is lethal to several cancers including lung cancer, breast cancer, and colorectal cancer." (PMID 34389703, 2021). "RBM39 depletion reduces tumorigenesis and cancer hallmarks of breast cancer cells." (PMID 34804951, 2021). "If the expression of RBM39 was inhibited, the proliferation of human breast cancer cells could be significantly reduced." (PMID 34389703, 2021). "In addition, Rbm39 (alias CAPERalpha) is able to alter the VEGF-121/VEGF-189 ratio in breast cancer cells." (PMID 21210965, 2010). "We then tested the degradation of RBM39 (nuclear) and SMS (cytoplasmic) N-terminally tagged with iTAG (DCD23) in CT26 and AT3 (murine mammary cancer lines)." (PMID 37360684, 2023).
breast cancer (continued). "Another study reported that RBM39 acts as a major transcriptional regulator and interacts with the MLL1 complex to promote breast cancer cell proliferation." (PMID 35989423, 2022). "RBM39 functions as a master transcriptional regulator that interacts with the MLL1 complex to facilitate chromatin binding and H3K4 trimethylation in breast cancer cells." (PMID 34804951, 2021). "In particular, RBM39, whose expression was increased 6.6-fold by GW9662, was recently reported to be increased in ER-dependent mammary tumors developing in caveolin-1 knockout mice." (PMID 22538444, 2012).
multiple myeloma (10 papers, 2021 to 2026). "It has been previously reported that the lncRNA DARS-AS1 bound to RBM39 and promoted the malignant progression of myeloma." (PMID 37198207, 2023). "Tong and fellows also found that DARS-AS1 facilitates myeloma progression by maintaining RNA-binding motif protein 39 (RBM39) stability." (PMID 35970927, 2022). "As a new oncogene in myeloma, RBM39 is essential for the proliferation of multiple myeloma cells and tumorigenesis." (PMID 34389703, 2021). "Its role has been established in multiple myeloma along the HIF1α/DARS-AS1/RBM39 axis that could be a useful target in multiple myeloma." (PMID 38571491, 2024). "DARS-AS1 induced myeloma cell tumorigenesis and survival via binding RBM39." (PMID 35422889, 2022). "Likewise, it has been shown that RBM39 plays an important role in multiple myeloma, by promoting multiple myeloma cell proliferation and inhibiting apoptosis under hypoxic conditions in vitro." (PMID 36076951, 2022). "Based on its biological role and clinical significance in tumor progression, RBM39 might become a key prognostic indicator for multiple myeloma patients." (PMID 34389703, 2021). "Moreover, this gene is directly upregulated by HIF1 gene, which stabilizes RBM39 protein in Myeloma." (PMID 34249670, 2021). "Therefore, targeting the RBM39 axis might be a potential therapeutic target for multiple myeloma." (PMID 34389703, 2021). "In myeloma 44, DARS-AS1 exerts its function by binding RNA-binding motif protein 39 (RBM39), which impedes the interaction between RBM39 and its E3 ubiquitin ligase RNF147 and prevents RBM39 from degradation." (PMID 38322590, 2024). "They demonstrated that DARS-AS1 is regulated by HIF-1α and that DARS-AS1 regulates mTOR signaling via RBM39, thus concluding that the HIF1α/DARS-AS1/RBM39 axis could be a useful target in multiple myeloma." (PMID 36076951, 2022). "In addition, further studies have shown that RBM39 inhibited the ubiquitination and degradation of RBM39 protein through the interaction with DARS-AS1, indicating that RBM39 might mediate the biological function of DARS-AS1 on multiple myeloma under hypoxic conditions." (PMID 34389703, 2021).
neuroblastoma (10 papers, 2021 to 2025). Neuroblastoma (NB) is the most common solid, extracranial childhood tumor. "Loss of RBM39 imposes significant survival pressure on neuroblastoma cells, forcing them to adapt by epigenetically reprogramming their cell state—either to restore RBM39 levels or to upregulate survival pathways and/or downregulate cell death programs." (PMID 40962798, 2025). "We then validated the interactions of JMJD6 with splicing factors using immunoprecipitation and western blot, and demonstrated that JMJD6 formed a complex with these RNA binding proteins, including RBM39, a therapeutic target of high-risk neuroblastoma." (PMID 38488852, 2024). "In neuroblastoma models, indisulam induces rapid loss of RBM39, accumulation of splicing errors and growth inhibition in a DCAF15-dependent manner." (PMID 35296644, 2022). "Here the authors show that high-risk neuroblastoma is sensitive to indisulam, a selective degrader of the splicing factor RBM39 through the dual targeting of RNA splicing and metabolism." (PMID 35296644, 2022). "To investigate the mechanisms underlying this plasticity, we subjected human and murine neuroblastoma models to repeated treatment with indisulam, a molecular glue compound that selectively degrades the splicing factor RBM39, until full drug resistance emerged." (PMID 41365913, 2025). "In conclusion, our findings suggest that MYCN-amplified high-risk neuroblastoma may be particularly sensitive to the selective loss of RBM39 and modulation of splicing and metabolism by indisulam." (PMID 35296644, 2022). "Moreover, indisulam-mediated RBM39 degradation leads to complete tumor regression in multiple, independent mouse models of high-risk neuroblastoma." (PMID 34788094, 2021). "First, indisulam degrades RBM39 in neuroblastoma cells, leading to cell death due to splicing defects, which is a major mechanism of indisulam in an immunodeficient setting." (PMID 40962798, 2025). "Our previous study showed that indisulam, the splicing inhibitor that targets RBM39, a JMJD6 interacting partner, induced a durable complete response in multiple high-risk neuroblastoma models, supporting its potential use in future clinical trials." (PMID 38488852, 2024). "Two recent studies demonstrated that targeting of the splicing regulator RBM39 using indisulam represents a novel therapeutic option for neuroblastoma." (PMID 39313128, 2024). "To confirm that indisulam induces selective RBM39 degradation in neuroblastoma, we performed LC–MS-based global label-free proteomics following indisulam treatment in IMR-32 cells." (PMID 35296644, 2022). "Analysis of public drug sensitivity data showed neuroblastoma lines to be sensitive to indisulam, a molecular glue that selectively targets RNA splicing factor RBM39 for proteosomal degradation via DCAF15-E3-ubiquitin ligase." (PMID 35296644, 2022). "To study the essentiality of DCAF15 in the mode of action of aryl sulfonamides in neuroblastoma, we generated DCAF15 knockout cells using CRISPR–Cas9 in KELLY in which loss of DCAF15 rescued acute RBM39 degradation from indisulam treatment (6 h, 10 μM)." (PMID 35296644, 2022). "The mechanism for why RBM39 is especially essential in MYC-driven neuroblastoma is an important question to address in the future and has the potential to reveal new targets." (PMID 34788094, 2021). "Here, we demonstrate that neuroblastoma is both dependent on RBM39 and expresses relatively high levels of DCAF15, providing a mechanistic rationale for indisulam treatment." (PMID 34788094, 2021). "In genome-wide RNAi screens, suppression of RBM39 had a greater impact on neuroblastoma proliferation than other lineages." (PMID 34788094, 2021). "Our data indicate that targeting the dysregulated spliceosome by precisely inhibiting RBM39, a vulnerability in neuroblastoma, is a valid therapeutic strategy." (PMID 34788094, 2021).